SMAD4 (SMAD family member 4)
Diseases named in the same sentence as SMAD4 in open-access papers (continued):
Sharing a sentence is not in itself a finding about the gene and the disease.
cancer (continued). "Furthermore, 11 KEGG pathways were also enriched, such as hsa05200:Pathways in cancer (CDKN1B, SMAD4), hsa04350:TGF-β signaling pathway (SMAD4) and hsa04110:Cell cycle (CDKN1B, SMAD4)." (PMID 31763681, 2020). "For the first time in this study, it was revealed that SMAD4, a major regulator of TGF-β signaling preceding cancer EMT and metastasis in advanced cancers, was a target for O-GlcNAcylation and that O-phosphorylation is interrupted during hyper-O-GlcNAcylation caused by OGT overexpression." (PMID 33199824, 2020). "On the other hand, the frequency of SMAD4 and PIK3CA mutation was higher in patients without germline cancer-associated variants (17% and 15%, respectively) than those with variants (8% and 8%, respectively)." (PMID 30850667, 2019). "Using DNA copy number data from 9,744 human cancer specimens, we demonstrate that linear deletion limitation exists and exposes deletion-limiting genes for seven known deletion targets (CDKN2A, RB1, PTEN, MAP2K4, NF1, SMAD4, and LINC00290)." (PMID 31341961, 2019). "Indeed, this family belongs to a superfamily that has been proposed as a pan-cancer oncogenic miRNA superfamily that targets prominent tumor suppressor genes (TSGs), such as TGFBR2, SMAD4, PTEN." (PMID 29744254, 2018). "As a control, we randomly selected 12 cancer type–matched cell lines without simultaneous mutations in KRAS and SMAD4 (hereafter referred to as Control cell lines) for which published in vitro radiosensitivity data were available." (PMID 30220971, 2018). "These included the well‐studied cases of CTNNB1, PIK3R1, and SMAD4 proteins as well as proteins that are as yet not annotated as drivers, but are functionally connected to cancer pathways." (PMID 29572294, 2018). "However, the role of SMAD4-differentially expressed miRNAs and/or proteins carried in PDAC-derived Exo, which transfer their cargo from cancer cells to immune cells thus altering their behavior should also be taken into account." (PMID 29156694, 2017). "In conclusion, SMAD4 homozygous deletion favors the constitutive activation of ERK, the EGF-induced activation of NF-κB and PI3K/AKT, and the EGF-induced inhibition of Wnt/β-catenin pathways, which are critical to cancer proliferation and metastases." (PMID 27655713, 2016). "Although it has been reported that miR-130a targeted Smad4 in granulocytic cells, another study did not support this report in human cancer cells." (PMID 26817584, 2016). "Studies have shown that downregulation of SMAD4 could counteract TGF-β-induced cell cycle arrest and promote EMT, resulting in increased motility and invasiveness of cancer cells." (PMID 26908446, 2016). "By contrast, wild-type SMAD4 immunoreactivity was not detectable in the cancer cells in 31 PDACs, and in these tissues CD31 immunoreactivity was sparse." (PMID 26586478, 2016). "For example, genes with Motif 1 in Molecular Mechanisms of Cancer pathway include MAPK1, BRAF, SMAD2, FZD5, FZD8, NOTCH1 and LRP1, whereas genes with Motif 2 and/or Motif3 in the same pathway include LRP5, LRP6, MDM2, CTNND1, SMAD3, SMAD4 and SMAD7." (PMID 26040697, 2015). "SMAD4/DPC4 protein functions are required in the regulation of TGF-β–inducible EMT, which plays an important role in embryogenesis, cell adhesion, cellular motility, and cancer cell invasion and metastasis." (PMID 25264609, 2014).
cancer (continued). "Correlation of drug activities with cancer gene mutations revealed novel drug sensitivity markers, suggesting that cancers dependent on mutant CTNNB1 will respond to trametinib and other MEK inhibitors, and cancers dependent on SMAD4 to small molecule EGFR inhibitor drugs." (PMID 24651269, 2014). "Non-recurrent, cancer-specific mutations (n = 28 genes across 11 cancers) predominantly correlated with high telomerase activity, with notable exceptions including PPP2R1A in UCS, HRAS, and GTF2I in THYM and SMAD4 in PAAD." (PMID 41321994, 2025). "However, directly targeting mutant SMAD4 for cancer therapy remains challenging due to the lack of system screening for drugs reactivating mutant SMAD4 function." (PMID 39727835, 2024). "We therefore proposed that the anti-metastatic activity of BMP4 could be mediated by SMAD4-dependent canonical signalling, and upon the loss of functional SMAD4, BMP4 could promote cancer progression through non-canonical signalling pathways." (PMID 38689334, 2024). "Moreover, several TFs play known roles in cancers, such as ASCL1, NCOR1, SMAD2, and SMAD4." (PMID 39716176, 2024). "Hence, the correlation between SMAD4 and TGF-beta is an important factor in cancer research." (PMID 39113194, 2024). "As a core component in TGFβ signaling, SMAD4 shows the highest response to TGFβ signaling by stabilizating or recruiting transcriptional factors and coactivators to gene regulatory elements in exquisite contexts, leading to the pleiotropic roles of TGF-β/SMAD4 in cancer progression." (PMID 37550764, 2023). "Statins may activate the bone morphogenetic protein (BMP) pathway because these drugs are more effective in SMAD family member 4 (SMAD4)-expressing cancers but not KRAS mutant tumors." (PMID 38023258, 2023). "Apparently, the EMT or EMT-like state of poor prognosis CMS4 cancers does not require SMAD4." (PMID 34857888, 2022). "Furthermore, PDAC cells with intact SMAD4 are more sensitive to TGF-β1 inhibitor treatment to reduce cell migration, whereas PDAC cells lacking SMAD4 showed decreased cell motility in response to EGFR inhibitor treatment in PDAC carcinoma tissue." (PMID 36127339, 2022). "Although some of our cases had SMAD4 mutations limited to the invasive cancer, most of the IPMN/MCN-associated cancers lacked driver gene alterations that were associated with invasive disease, suggesting that malignant progression is not universally driven by point mutations." (PMID 32796935, 2020). "So, while cancer cells would generally benefit from abrogating BMP signaling, cancer cells with a non-functional canonical pathway (e.g., due to loss of SMAD4) could profit from active BMP signaling." (PMID 32486027, 2020). "As the main effector of TGF-β signaling, SMAD4 has been found to be non-functional in more than half of adenocarcinomas of the pancreatic duct, and to varying degrees, in several other types of cancers." (PMID 31867281, 2019). "Using DNA copy number copy number data from 9744 cancer specimens belonging to 39 cancer subtypes, we show that linear deletion limitation exists, and exploit it to expose deletion-limiting genes for seven deletion targets (CDKN2A, RB1, PTEN, MAP2K4, NF1, SMAD4, and LINC00290)." (PMID 31341961, 2019). "As these genes besides APC, KRAS and SMAD4 are listed in neither of the cancer Census Genes nor the COSMIC CRC genes, they might be passenger mutations or HGCA-specific mutations that might not play an important role in HGCA progression to CRC." (PMID 28179590, 2017). "The biomarkers of EMT were not highly specific to cancer cells, but immunostaining for SMAD4—a key node in signal transduction relating to EMT and other functions—may be useful for predicting distant metastasis." (PMID 28642461, 2017).
cancer (continued). "The morphology was most consistent with a carcinoma that spread from the pancreaticobiliary system and immunolabeling for SMAD4 demonstrated retention of labeling, which neither confirmed nor refuted an interpretation of spread from a pancreaticobiliary lesion." (PMID 29246032, 2017). "However, there are no studies on the effect of HDAC inhibitors on SMAD4 nuclear translocation in any cancer." (PMID 26726879, 2016). "Our findings suggest that S100 proteins, by targeting NF-κB signaling, may counteract cancer progression in Smad4 positive, but not in Smad4 negative, PDAC." (PMID 24670043, 2014). "Cancer cells also displayed significant moderate to strong relationships between cytoplasmic and nuclear levels for several proteins: p-ERK (ρ = 0.72, p < 0.001), p-p38 (ρ = 0.56, p = 0.004), T308p-PKB (ρ = 0.52, p = 0.007), SMAD4 (ρ = 0.63, p < 0.001) and PTEN (ρ = 0.87, p < 0.001)." (PMID 18254976, 2008). "The "classical" cell cycle-associated TGF-β target genes were, however, not induced under these conditions, suggesting that growth responses in these cells in vitro do not reflect physiological mechanisms in cancer cells but occur only upon excessive Smad4 overexpression." (PMID 17997817, 2007). "There was no survival effect for the presence or absence of TβRI, which is much less prevalently altered in cancer than the ligand-binding TβRII, whereas the effect of Smad4 could still be seen in this stratification." (PMID 16438724, 2006). "Furthermore, bioinformatic analysis of miR‐34a targets in various cancers identifies numerous target genes such as Jagged 1 (JAG1), CD44, SRY (sex determining region Y)‐box 4 (SOX4), Notch homolog 2 (NOTCH2), Matrix metallopeptidase 9 (MMP9), Interleukin 6 (IL‐6), and SMAD family member 4 (SMAD4)." (PMID 40336533, 2025). "Furthermore, the deacetylation of SMAD4 through SIRT7 has the potential to function as a blocker for TGF-β, which may be of relevance when targeted therapy is needed for appropriate individuals with cancer." (PMID 38316768, 2024). "To investigate whether SETD2 exacerbates SMAD4‐dificiency CRC, we first consulted the clinical data samples of CRC in the TCGA database and analysed the expression levels of SETD2 and SMAD4 in the samples of CRC patients and their relationship with cancer stage and survival rate." (PMID 37962020, 2023). "However, Smad4 is also known to be inactivated in more than 50% of PDAC patients, and several in vitro studies have indicated that both AsPC1 and BxPC3 lack Smad4 protein expression, therefore its contribution to signal transduction is negligible in regards to these particular cancer cell lines." (PMID 29064388, 2017). "During advanced stages of carcinogenesis, cancer cells become resistant to the protective effects of TGF-β by different mechanisms, including modifications in the components of TGF-β signaling, such as inactivating mutations in TβRII and Smad4, and other not fully elucidated alterations." (PMID 26078812, 2015). "Defective TGFβ signaling in cancer cells, mostly through the inactivation of TGFβRII in MSI CRC or SMAD4 in non-hypermutated CRC, is a frequent event that has been implicated in CRC progression." (PMID 37190048, 2023). "After cancer cells were stimulated with TGFβ, R-SMAD2 and R-SMAD3 were phosphorylated and formed heterodimers that entered the nucleus in the absence of SMAD4." (PMID 35942952, 2022).
cancer (continued). "In summary, through data analysis, imaging and functional assays in in vitro and in vivo preclinical models, we demonstrated the anti-cancer effects and feasibility of selectively targeting BMP2/4 in SMAD4 negative EAC by novel anti BMP4 and BMP2/4 VHHs." (PMID 35902550, 2022). "We further detected the expression of some reported stemness-related genes in HCC and CRC stem cells including CTNNB1, HES1, SMAD4, GLI1, STAT3 and BMI122, 23, 24, 25 in the cancer cell lines with or without PS341 treatment." (PMID 26915315, 2016). "It is also consistent with the concept of an absent upregulation of p21 after abrogation of the TGFβ/SMAD4 axis, which can be explained by knockdown of SMAD4, as in our experiments, but also by absence of TGFBR2, as seen in the cancer samples." (PMID 22761777, 2012). "Interestingly, the NS1643 reprogramming of cancer cells occurred only in HT29 and FET but not in SW480 cells, which are known to lack SMAD4, a major component of the TGFβ signaling, even though these cells express a functional Kv11.1 channel." (PMID 34885136, 2021). "While all activins commonly trigger Smad4 through ALK4, Act-B and -AB, but not Act-A, could also provoke Smad4-dependent actions via ALK7, which has been reported to potently inhibit cell proliferation and survival in several human cancer cell lines." (PMID 34867090, 2021).
adenocarcinoma (44 papers, 2012 to 2025). A common cancer characterized by the presence of malignant glandular cells. "The SMAD4 mutation was associated with adenocarcinomas exhibiting mucinous morphology, which portends a poorer prognosis, while the most prevalent mutation of IDH1 is the R132C variant, which occurs in 20% of cases." (PMID 39199671, 2024). "The adenocarcinoma component showed an exclusive amplification of KRAS as well as a SMAD4 mutation." (PMID 40833530, 2025). "Also, loss of SMAD4 immunohistochemistry is frequently used in daily practice to suggest pancreatic origin of an adenocarcinoma in a distant site in a patient with a pancreatic mass." (PMID 27267993, 2016). "Furthermore, sample 5557 had two somatic mutations in Wnt (FBXW7) and TGFβ (SMAD4) pathways, and this patient also suffered a poorly differentiated adenocarcinoma in transverse colon." (PMID 25617745, 2015). "Along this line, SMAD4 mutations, quite common in PDAC (around 50% of cases), were rarely observed in our cohort of mucinous cysts and associated adenocarcinomas (14% of cases)." (PMID 40371932, 2025). "Histologically, KRAS/SMAD4 KO tumors were moderately differentiated adenocarcinomas exhibiting glandular growth patterns." (PMID 33674596, 2021). "Reportedly, microadenoma, macroadenoma to invasive well-differentiated adenocarcinoma were rapidly observed in the gastric Lgr5+ stem cells with the double deletion of Smad4 and PTEN using Lgr5-Cre mice." (PMID 33425768, 2020). "The results indicated that there were significant positive correlations among FSTL1, BMP4, Smad4, and p-Smad1/5/8 IHC expression in adenocarcinoma." (PMID 28852126, 2017). "For instance, a study on mutant cis-Apc/Smad4 mice spontaneously developing adenocarcinoma of the intestine demonstrated two-fold higher expression of Ccl9 mRNA in polyps than in wild-type C57BL/6, as well as five-fold higher expression of CCL9 protein in polyps than of Apc+/D716 mice." (PMID 37185750, 2023). "Accordingly, Smad4 expression gradually decreases in EAC metaplasia hyperplasia adenocarcinoma." (PMID 34568328, 2021). "We did not detect mutations of the BRAF, APC, or SMAD4 genes in the adenocarcinomas, although these genes have been reported as frequently mutated in previous studies." (PMID 34422662, 2021). "We found higher SMAD4 expression in adenocarcinomas compared with other types of NSCLC (P = 0.02)." (PMID 28199217, 2017). "A previous study showed that MMP7 was not required for malignant cell invasion in Smad4-deficient adenocarcinomas." (PMID 25424420, 2014). "Thus MMP7 is not needed for tissue invasion in Smad4-deficient adenocarcinomas." (PMID 25424420, 2014). "In contrast, some genes related to the “epithelial-mesenchymal transition (EMT) process” and the “stem cell properties”, including RNF43, CDH1, and SMAD4, as well as the related TGF-β signaling pathway have been observed more frequently altered in SRCC than in conventional adenocarcinoma (AC)." (PMID 34381313, 2021). "Downregulation of SMAD4 expression has been identified in pancancer transcriptome analysis to be characteristic for adenocarcinoma independent of origin." (PMID 32198650, 2020).
adenocarcinoma (continued). "NGS of routine biopsy samples from an exceptional non-responder identified SMAD4 as a driver of the aggressive course and supports derivation of NePC from primary adenocarcinoma (transdifferentiation)." (PMID 26444865, 2015).